IFIT2 (interferon induced protein with tetratricopeptide repeats 2)
Diseases named in the same sentence as IFIT2 in open-access papers (continued):
Sharing a sentence is not in itself a finding about the gene and the disease.
melanoma (11 papers, 2010 to 2025). A malignant, usually aggressive tumor composed of atypical, neoplastic melanocytes. "We focused on the potential prognostic value of EDN3, CLEC4E, SRPX2, KIR2DL4, UBE2L6, and IFIT2 as immune scores for melanoma patients." (PMID 34660598, 2021). "In SKCM, low expression levels of IFIT3, similar to IFIT1 and IFIT2, have been found to be correlated with patients’ poor overall survival and DSS and decreased sensitivity of melanoma cells to dasatinib and T-cell killing and apoptosis." (PMID 40564154, 2025). "The IHC staining results showed that Ube2L6, SRPX2, and IFIT2 were expressed at higher levels, while CLEC4E, END3, and KIR2DL4 were expressed at lower levels in 25 melanoma specimens." (PMID 34660598, 2021). "According to immunohistochemistry staining results, Ube2L6, SRPX2, and IFIT2 were expressed at higher levels, while CLEC4E, END3, and KIR2DL4 were expressed at lower levels in 25 melanoma specimens." (PMID 34660598, 2021). "Conversely, overexpressing IFIT1, IFIT2 and IFIT3 in human melanoma cell lines enhanced the sensitivity of human melanoma cell lines to T-cell killing, thereby recapitulating the effects of ganetespib treatment." (PMID 28878208, 2017). "Over-expression of SOCS proteins in melanoma cell lines led to significant inhibition of Tyr701-phosphorylated STAT1 (P-STAT1) and gene expression following stimulation with IFN-α (IFIT2, OAS-1, ISG-15) or IFN-γ (IRF1)." (PMID 20398276, 2010). "Genes, such as IFIT2, CCR10, and TMEM97, are important for the invasion of various cancer cells, such as oral cancer, melanoma, and glioma, but these genes may be responsible for the invasion of BRCA cells." (PMID 31311202, 2019). "Upregulation of interferon response genes in multiple melanoma cell lines by ganetespib was confirmed by quantitative real time PCR and Western blot analyses, most strongly for members of the IFN-induced protein with tetratricopeptide repeats (IFIT) gene family: IFIT1, IFIT2 and IFIT3." (PMID 28878208, 2017). "Melanoma patients lacking clinical responses to the anti-CTLA-4 immunotherapeutic, ipilimumab (as compared to those who had such responses) harbored a much higher rate of genomic defects in the IFN-γ pathway genes, including genetic losses of IFIT1, IFIT2 and IFIT3." (PMID 40564154, 2025).
gastric cancer (10 papers, 2016 to 2024). A primary or metastatic malignant neoplasm involving the stomach. "The observation of decreased IFIT2 expressions in lung and gastric cancer that is associated with tumor progression and poor survival supports its tumor suppressor function." (PMID 35386334, 2022). "In our present study, we found that IFIT2, the miR-375 targeted gene, was decreased in gastric cancer by loss of lncRNA GRIK1-AS1 which competitively sponges miR-375." (PMID 34660323, 2021). "GRIK1-AS1 serves as a sponge for miR-375, leading to increased IFIT2 protein levels and the promotion of gastric cancer progression." (PMID 38408075, 2024). "Our direct experimental evidence based on a series of rescue experiments and RNA-pull down assays directly confirmed the regulatory relationship between GRIK1-AS1 and miR-375/IFIT2 axis using gastric cancer cell lines." (PMID 34660323, 2021). "In summary, we identify a novel regulatory mechanism of GRIK1-AS1 with miR-375 and its direct target IFIT2 in gastric cancer." (PMID 34660323, 2021). "In this study, we demonstrated a regulatory relationship between lncRNA GRIK1-AS1 and miR-375/IFIT2 axis in gastric cancer." (PMID 34660323, 2021). "Together, these results corroborated that GRIK1-AS1/miR-375/IFIT2 axis is a novel regulatory mechanism in gastric cancer progression." (PMID 34660323, 2021). "Real-time qPCR and western blotting analyses indicate a significant (AGS vs GES-1: P<0.005, SGC-7901 vs GES-1: P<0.005, HGC27 vs GES-1: P<0.01) lower expression level of IFIT2 in gastric cancer cells than in gastric epithelial cells." (PMID 34660323, 2021). "The functional significance of the GRIK1-AS1/miR-375/IFIT2 axis in gastric cancer progression and metastasis supports the future development of GRIK1-AS1 based therapeutic development." (PMID 34660323, 2021). "In this study, we discovered a novel regulatory mechanism of lncRNA GRIK1-AS1 with miR-375 and functional impact on gastric cancer through IFIT2 as the major target." (PMID 34660323, 2021). "We discovered that IFIT2 was one of the direct key downstream target genes of miR-375, and established the important role of the GRIK1-AS1/miR-375/IFIT2 axis in the progression of gastric cancer." (PMID 34660323, 2021). "Functionally, the over-expression of miR-375 or knockdown of IFIT2 perfectly reversed the suppressed cell proliferation and invasive capability caused by GRIK1-AS1 over-expression in gastric cancer cells." (PMID 34660323, 2021). "We have previously reported that decreased IFIT2 expression was found in gastric cancer tissues, and its expression level was significantly associated with tumor stage and postoperative prognoses of the patients." (PMID 34660323, 2021). "For HER2+ gastric cancer, the high expression of VIM, IFI44, IFI44L, IFIT2, IFIT3, ISG15, OAS1, or OASL was associated with worse overall survival (P < 0.05)." (PMID 31949544, 2019). "For all gastric cancer cases, our results showed that high ERBB2 expression was associated with the worse overall survival of GC patients, VIM, IFI44, IFIT2, and MX1 showed similar associations (P < 0.05)." (PMID 31949544, 2019). "Taken together, our results revealed a novel mechanism of GRIK1-AS1 as a sponge to miR-375 that impacts gastric cancer progression via modulating target mRNA IFIT2 translation, and as a result, opens a new strategy to future GRIK1-AS1 based therapeutic development." (PMID 34660323, 2021). "Importantly, they found that exogenous expression of IFIT2 significantly suppressed the growth of gastric cancer cells, and promoted apoptosis in the cells treated with Adriamycin." (PMID 29245969, 2017). "IFIT2 is a tumor suppressor gene in gastric cancer, promoting apoptosis and cell death." (PMID 27902465, 2016). "The expression of PSMB8, IFIT2, and IFIT1 had prognostic value in gastric cancer at different stages." (PMID 31949544, 2019).
osteosarcoma (10 papers, 2017 to 2025). A usually aggressive malignant bone-forming mesenchymal neoplasm, predominantly affecting adolescents and young adults. "Increased IFIT2 levels activate the TNF/NF-κB pathway—a pivotal driver of osteosarcoma—resulting in enhanced cell proliferation, suppressed apoptosis, and heightened invasive and metastatic capacities." (PMID 40426910, 2025). "The degradation of L3MBTL2 leads to elevated IFIT2 expression, which is upregulated in osteosarcoma and correlates with tumor progression and poor prognosis." (PMID 40426910, 2025). "By stabilizing L3MBTL2, ATO suppresses IFIT2 gene expression, ultimately inhibiting osteosarcoma cell proliferation and tumor growth." (PMID 40426910, 2025). "Additionally, this lncRNA ameliorates the resistance of osteosarcoma cells by targeting the signaling axis comprising the miR-645-interferon-induced with tetratricopeptide repeats 2 (IFIT2)." (PMID 39015175, 2024). "In summary, UBE2O promotes osteosarcoma progression by degrading L3MBTL2, disrupting its nuclear condensates, derepressing IFIT2 transcription, and activating the TNF/NF-κB pathway." (PMID 40426910, 2025). "IFIT2, a key mediator of the TNF/NF-κB signaling pathway, plays a critical role in osteosarcoma progression." (PMID 40426910, 2025). "LINC00161 upregulates interferon-induced protein with tetratricopeptide repeats 2 (IFIT2), a cell death-promoting factor, augmenting cisplatin-induced apoptosis in osteosarcoma cells." (PMID 35055115, 2022). "For example, Wang Y demonstrated that lncRNA LINC00161 could bind miR-645, which was reported to target IFIT2, and regulated IFIT2 expression via miR-645; and LINC00161 sensitized osteosarcoma cells to cisplatin-induced apoptosis through regulation of the miR-645-IFIT2 axis." (PMID 28415557, 2017).
oral squamous cell carcinoma (9 papers, 2019 to 2026). "Studies have shown that IFIT2 depletion induces cell migration and is associated with poor prognosis in patients with oral squamous cell carcinoma (OSCC)." (PMID 31949544, 2019). "Studies have shown that IFIT2 depletion can lead to up-regulation of TNFα promoting angiogenesis, metastasis, epithelial-mesenchymal transition, cell migration, and invasion of oral squamous cell carcinoma." (PMID 37046696, 2023). "IFIT2 has been identified as a tumor suppressor in several tumor types, such as oral squamous cell carcinoma, breast cancer, gallbladder cancer, and lung cancer." (PMID 35094011, 2022). "We previously showed the depletion of IFIT2 enhanced cell migration and metastatic activity in oral squamous cell carcinoma (OSCC) cells via the activation of atypical PKC signaling." (PMID 33256074, 2020). "TNF-α secretion, leading to angiogenesis and metastasis of oral squamous cell carcinoma, can be regulated by IFIT2 depletion." (PMID 30875792, 2019). "In oral squamous cell carcinoma (OSCC), IFIT1 and IFIT3 promote metastasis, while IFIT2 exhibits the opposite effect." (PMID 36851555, 2023). "Studies demonstrated a correlation between IFIT2 down‐regulation and EMT induction, metastasis and multi‐drug resistance in patients with oral squamous cell carcinoma (OSCC)." (PMID 35810383, 2022). "Our previous studies demonstrated that IFIT2 interacted with the cytoskeleton and that its depletion induced epithelial-mesenchymal transition (EMT) in oral squamous cell carcinoma (OSCC) cells." (PMID 33256074, 2020).
breast cancer (7 papers, 2018 to 2025). A primary or metastatic malignant neoplasm involving the breast. "Using database analysis, the expression of IFIT2 was positively correlated with immune infiltration of the tumor and high IFIT2 expression was associated with a decreased 5-year survival rate of breast cancer patients." (PMID 40564154, 2025). "Further studies are needed to identify the underlying mechanisms regulated by IFIT2 in resistant breast cancer cells and to investigate the therapeutic effects of IFIT2 on a variety of cancer types possessing high CSCs and expressing resistance." (PMID 30875792, 2019). "The upregulation of IFIT2 can suppress the CSC-like characteristics of radio/chemoresistant breast cancer cells." (PMID 36979874, 2023). "IFIT2 was considered a tumor suppressor in breast cancer, as it had been identified to inhibit cancer cell growth and migration, and promoted cell apoptosis." (PMID 37968615, 2023). "IFIT2 expression was decreased in metastatic breast cancer compared to primary tumor or normal tissue (n = 1247, one-way analysis of variance [ANOVA], p-value = 0.0014, f = 6.593)." (PMID 30875792, 2019). "To determine the role of IFIT2, we used Xena browser and the Kaplan-Meier plotter to analyze the relationships between IFIT2 expression levels and the progression of The Cancer Genome Atlas (TCGA) breast cancer cohort and the survival rate of TNBC patients." (PMID 30875792, 2019). "More controversies exist in terms of the role of IFIT2 in breast cancer." (PMID 40564154, 2025). "Therefore, we propose that the IFIT2 gene is critical for treatment resistance in breast cancer and plays an important role in overcoming resistance with baicalein." (PMID 30875792, 2019).
encephalitis (5 papers, 2014 to 2023). An acute inflammatory process affecting the brain parenchyma. "As in prior studies, an accumulation of IFIT2 has been found in JE, and IFIT2 deficiency triggered uncontrolled neurotropic coronavirus infection with enhanced encephalitis." (PMID 37752509, 2023). "One recent study demonstrated that IFIT2 deficiency results in uncontrolled coronavirus replication and enhanced encephalitis via impaired IFN-α/β induction in macrophages." (PMID 25360880, 2014). "Interestingly, despite increased viral load with minimal changes in the expression of selected cytokines and chemokines, Ifit2-/- mice exhibited reduced encephalitis as evident by decreased perivascular cuffing, and reduced formation of microglial nodules." (PMID 33253295, 2020). "Enhanced disease severity of RSA59 infected Ifit2-/- relative to WT mice was accompanied by increased viral load and spread throughout the brain, although development of encephalitis marked by perivascular cuffing and formation of microglial nodules was greatly impaired." (PMID 33253295, 2020). "Previously, overexpression of murine Ifit2 was shown to slightly inhibit the replication of both WT and cap0-mutant MHV, whereas Ifit2 knockout increased replication of neurotropic MHV and exacerbated viral encephalitis." (PMID 33454014, 2020). "In MHV-induced encephalitis, IFIT2 is a positive regulator of IFNα/β expression rather than a direct antiviral mediator, with Ifit2-/- mice showing significantly reduced expression of IFN-α/β and the downstream ISG mRNAs (Ifit1, Isg15, and Pkr)." (PMID 36325336, 2022).
HCMV infection (5 papers, 2015 to 2025). "Surprisingly, accumulation of IFNB1 mRNA and a representative ISG-encoded polypeptide (IFIT2 protein) were significantly reduced in response to HCMV infection when cells were treated with TIF-IA siRNA compared to non-silencing siRNA." (PMID 31841110, 2019). "Several ISGs, including IFIT1, IFIT2, IFIT3, Mx1, Mx2, CXCL10 and ISG15 were found to be upregulated transcriptionally following HCMV infection independently of type I IFN-initiated JAK-STAT signaling, but dependent on intact IRF3 signaling." (PMID 30871003, 2019). "Studies of HCMV infection in the presence of cycloheximide (CHX) have shown upregulation of IFIT1 (IFI56), IFIT2 (ISG54), IFIT3 (cig49, ISG60), MxA (the protein produced from the Mx1 gene) and ISG15." (PMID 30871003, 2019). "Induction of the IFN-independent ISG viperin during HCMV infection is known to be induced by either IRF3 or IRF1, binding directly to its promoter, and this may also be the mechanism of IFIT1, IFIT2, IFIT3, CXCL10, Mx1, Mx2 and ISG15 upregulation." (PMID 30871003, 2019).
influenza (5 papers, 2011 to 2025). An acute viral infection of the respiratory tract, occurring in isolated cases, in epidemics, or in pandemics; it is caused by serologically different strains of viruses (influenzaviruses) designated A, B, and C, has a 3-day incubation period, and usually lasts for 3 to 10 days. "In conclusion, IFIT1 and IFIT2 are anti-influenza proteins through their inhibitory effects on viral RNA synthesis." (PMID 37515100, 2023). "In addition, Itraconazole, a broad-spectrum triazole fungicide, which is also widely used in the fight against influenza and HIV, significantly promotes IFIT2 expression." (PMID 38737277, 2024).
atherosclerosis (4 papers, 2018 to 2025). A disease characterized by the build-up of fatty material and calcium deposition in the arterial wall resulting in partial or complete occlusion of the arterial lumen. "IFIH1, IFIT1, IFIT2, IFIT3, ISG15 and OAS3 had similar expression differences to the training set and had good diagnostic abilities for atherosclerosis." (PMID 36437453, 2022). "Nevertheless, our data indicate that atherosclerotic mice lacking TACI signaling in myeloid cells express increased amounts of typical TLR9-induced genes, such as Ifit2 and Cxcl10 transcripts, in their spleens and developed increased atherosclerosis." (PMID 29858401, 2018). "A previous study identified IFIT1, IFIT2, IFIT3, and ISG15 as immune-related hub genes of atherosclerosis." (PMID 38397063, 2024). "IFIT3, IFIT2 and IFIT1 were the top three proteins potentially playing key roles in atherosclerosis." (PMID 36437453, 2022). "Our study identified IFIH1, IFIT1, IFIT2, IFIT3, ISG15 and OAS3 as immune-related hub genes of atherosclerosis." (PMID 36437453, 2022).
cholangiocarcinoma (4 papers, 2022 to 2024). A carcinoma that arises from the intrahepatic biliary tree (intrahepatic cholangiocarcinoma) or from the junction, or adjacent to the junction, of the right and left hepatic ducts (hilar cholangiocarcinoma). "Interferon-induced protein with tetratricopeptide repeats 2 (IFIT2) has also been identified as a target of METTL3 in cholangiocarcinoma." (PMID 38365891, 2024). "Recent evidence showed that METTL3 promotes cholangiocarcinoma progression by YTHDF2-mediated IFIT2 mRNA degradation." (PMID 38267969, 2024). "Interestingly, METTL3 was recently reported to regulate IFIT2 expression in a m6A-YTHDF2-dependent manner in cholangiocarcinoma." (PMID 36386128, 2022). "Immunohistochemical results revealed that the expression of RIG-I, MAVS, cGAS, IRF3, MDA5, IFIT2, and IRF7 was significantly higher in liver tissue slices from patients with cholangiocarcinoma than in the control group." (PMID 38817870, 2024). "We analyzed the expression levels of Type I interferons and ISG genes in the tumor tissues of patients and normal control tissues, revealing a consistent upregulation of ISG genes, including ISG15, MX1, MDA5, IFIT2, IFIT3, IRF1 and IRF7, in the tumor tissues of patients with cholangiocarcinoma." (PMID 38817870, 2024).